VHL (von Hippel-Lindau tumor suppressor)
Diseases named in the same sentence as VHL in open-access papers (continued):
Sharing a sentence is not in itself a finding about the gene and the disease.
tumor (continued). "Moreover our analysis showed a statistically significant association between allele G and genotypes AG and GG of rs779805 in the VHL tumor suppressor gene and high (G3 and G4) nuclear grade." (PMID 38115281, 2023). "Finally, we evaluated the associations of the VHL polymorphisms with AJCC TNM pathologic stage of the primary tumor." (PMID 38115281, 2023). "Overexpression of MET may be the primal causative event in tumor invasion and metastasis induced by VHL loss suggesting its utility as a potential downstream candidate in the context of HIF-α overexpression." (PMID 36831657, 2023). "In summary, we identify a novel regulatory function of VHL in relation to SCD5 and fatty acid metabolism, and propose a new mechanism of how loss of VHL may contribute to ccRCC tumor formation and progression." (PMID 36980176, 2023). "In fact, tumor growth was suppressed upon reconstitution of CPT1A in VHL-deficient ccRCC in vivo." (PMID 36831657, 2023). "For example, cells from patients with VHL-deficient tumours could be used to assess whether the general findings observed here apply broadly across the syndrome." (PMID 37506952, 2023). "Furthermore, results from xenograft experiments showed that RO-3306 inhibited tumor growth and increased sensitivity to cisplatin, which was also largely abrogated by the deficiency of VHL." (PMID 36813923, 2023). "Future studies are needed to further determine whether and how reductive stress affects the metabolism of glucose, lipids, and glutamine in VHL-deficient tumour tissues." (PMID 37506952, 2023). "Increased HIF-1α activity results from loss of function of the VHL tumour suppressor gene." (PMID 36661719, 2023). "Biallelic VHL gene inactivation in ccRCC can occur via point mutation, indels (insertion or deletion mutations), loss of alleles on chromosome 3p25 and epigenetic alterations including hypermethylation of the VHL gene promoter resulting in a loss of the tumor suppressor function of pVHL." (PMID 36831657, 2023). "The L169P VHL variant is comparable to WT VHL in terms of protein stability, ability to degrade HIF1α factors and ability to regulate hypoxia gene expression, as well as in the suppression of ccRCC tumor cell growth." (PMID 37762376, 2023). "However a significant associations were found between allele G and genotypes AG and GG of rs779805 in the VHL tumor suppressor gene and increased tumor size, as well as high nuclear grade." (PMID 38115281, 2023). "This heterogeneity of VHL loss within one tumor may be due to the simultaneous development of two cell populations, each developed from a precursor cell where VHL loss did or did not occur." (PMID 38139136, 2023). "Following the initial identification of hypoxia-inducible factors (HIF) as important substrates of CRL2VHL, the list of CRL2VHL targets continues to expand, providing further insights into the molecular mechanisms underlying the tumor suppressive functions of VHL." (PMID 37850636, 2023). "In certain cases of VHL disease, the fast growth of Hbs may occur due to the accumulation of the already present loss of function (LOF) of the VHL gene with somatic mutation(s) in other tumour-related gene(s)." (PMID 37843608, 2023). "In summary, we have presented the mutational spectrum of the sporadic, non-VHL-HBL tumor using NGS." (PMID 37273678, 2023). "We have previously provided evidence that a discrete VHL point mutation, the most common VHL point mutation R167Q in hereditary VHL disease, interferes with tumor plasticity and may impact cell behavior by exacerbating phenotypic switching." (PMID 38201462, 2023). "Notably the VHL normal samples clustered more closely with their associated tumor than with the other VHL normal, suggesting that any methylation differences were patient specific rather than tumor specific." (PMID 36455002, 2022). "VEGF is a protein inhibited by a kind of tumor suppressor that is usually encoded by the VHL gene." (PMID 35299739, 2022).
tumor (continued). "We show that a VHL loss-dependent reprogramming of branched-chain amino acid catabolism sustains the de novo biosynthesis of aspartate and arginine enabling tumor cells with the flexibility of partitioning the nitrogen of the amino acids depending on their needs." (PMID 36539415, 2022). "Interestingly, the angiogenic tumor phenotype is seen in cells expressing VHL variants in which the HIFα-degrading function remains intact but the collagen IVα2-interacting function is lost." (PMID 36077607, 2022). "An intriguing molecular link between VHL mutation as the main truncal ccRCC driver mutation and secondary mutations in the different ccRCC epigenetic tumor suppressor genes is that these proteins all normally control aspects of DNA repair and DNA damage signaling." (PMID 36413415, 2022). "VHL mainly functions as a tumor suppressor gene, encoding two isotypes of the protein pVHL." (PMID 36557960, 2022). "The predominantly metastatic tumours in our cohort contained more frequent mutations in several genes such as SETD2, APC, KDM5C, HIF1A, RBM10, TRAK1 and FBXW7, while we detected lower mutation rates in VHL compared to the primary tumours analysed in the TCGA study." (PMID 35231161, 2022). "Interestingly, about 50% of the mutations occurring in tumor derived VHL are found in the CCT binding site." (PMID 35602608, 2022). "NEO cells were confirmed by inference of aneuploidy (InferCNV), showing chromosomal loss profiles concordant with SNP-array data (where available) and loss of heterozygosity for PCPG tumor-suppressor driver genes including VHL (chr3p), NF1 (chr17q), TMEM127 (chr2q) and SDHB (chr1p)." (PMID 36271074, 2022). "VHL is an important tumor suppressor gene, and VHL mutations induce renal carcinogenesis." (PMID 36267974, 2022). "Of note, VHL mutation is a major genetic driver in ccRCC tumor growth." (PMID 35740533, 2022). "Finally, inhibiting proteolysis by targeting LONP1 increases mitochondrial content in VHL-deficient cells and sensitizes therapy-resistant tumours to sorafenib treatment." (PMID 35760869, 2022). "On the other hand, pheochromocytoma (PCC) and non-secretory pancreatic islet cell cancers are caused by mutations in the VHL tumor suppressor and are characterized by marked interfamilial variations in frequency, significant morbidity and, sometimes, even mortality." (PMID 36699028, 2022). "VHL is a tumor suppressor gene often mutated in ccRCC patients." (PMID 35798829, 2022). "VHL is an autosomal dominant disease caused by genetic aberration of the tumor suppressor gene." (PMID 34963877, 2022). "If the tumor profile showed mono-allelic loss of VHL, it would be plausible that the germline VHL variant may in fact be deleterious." (PMID 35774415, 2022). "The VHL gene encodes the VHL protein (pVHL), which is a tumor suppressor." (PMID 36384467, 2022). "Moreover, GAL3ST1 is an HIF1 target gene, and its expression is induced upon loss of von Hippel-Lindau (VHL) tumor suppressor, leading to accumulation of its enzymatic product sulfatide." (PMID 35659268, 2022). "The complexity of phenotype–genotype associations between VHL aberrations and disease is further demonstrated by research data that VHL genetic aberrations follow the so-called continuum model of tumor suppression, which accounts for the zygosity status of genetic change and tissue specificity." (PMID 35205407, 2022). "First, an improved understanding of the natural history of VHL-disease associated neoplasms including variation in interpatient and organ-specific growth kinetics could assist with clinical decision making regarding the timing of belzutifan initiation." (PMID 36358730, 2022). "Von Hippel–Lindau (VHL) is a tumor suppressor whose loss is frequently seen in ccRCC patients." (PMID 36149322, 2022). "The loss of VHL promotes a loosely organized and angiogenic matrix environment that may represent one of the first steps in tumor formation." (PMID 36077607, 2022).
tumor (continued). "VHL tumor syndrome is caused by mutations in VHL tumor suppressor gene." (PMID 35528020, 2022). "Finally, we used targeted NGS to identify the presence of RCC specific mutations, such as VHL, or other cancer specific alterations in samples from different tumour grades and matched healthy tissue which had been grown in the stiff 3D cultures." (PMID 35102500, 2022). "However, LCN2's role in the VHL-mutation-mediated progression of tumor formation via the regulation of oxidative homeostasis and mitochondrial metabolism has not been previously studied." (PMID 34257811, 2021). "This may represent a novel mechanism whereby loss of VHL affects organ integrity and tumor behavior." (PMID 34290272, 2021). "While it is well admitted that VHL mutations play a significant role in regulating the development, invasiveness, and survival characteristics of RCC, the role of R167Q VHL mutation in modulating tumor plasticity remains unknown." (PMID 34359798, 2021). "Moreover, ccRCC is a highly vascularized cancer that is frequently associated with mutations in the von Hippel–Lindau (VHL) gene that promotes the angiogenic pathway and can be further subclassified into those with proangiogenic and proinflammatory tumours." (PMID 34503211, 2021). "Characteristic genetic features that differ this tumour from clear cell and papillar renal cell carcinoma may include VHL gene mutations and 3p losses." (PMID 35008576, 2021). "We recommend that patients with HGBs, especially those with VHL-associated HGBs, require immediate surgery when CNS symptoms appear or when radiological characteristics of asymptomatic tumors indicate an increase in tumor volume." (PMID 34109129, 2021). "When cellular context is paramount, whether genetic defects such as VHL mutation are present in a progenitor stem-like cell or progeny differentiated cell will determine the tumor subtype, the malignant potential, and the clinical outcome." (PMID 34439162, 2021). "In the first part of this review, we introduce the VHL protein (pVHL) encoded by the VHL tumor suppressor gene, which is part of the ubiquitin ligase complex that is essential for the specific degradation of HIF, in the context of the actual clinical findings of Von Hippel-Lindau (VHL) disease." (PMID 34884197, 2021). "Mutations of VHL can cause HIF1α stabilization, inducing sustained tumor angiogenesis." (PMID 34117220, 2021). "Furthermore, we demonstrated CPSF6 negatively regulated von Hippel Lindau (VHL), the gene encoding a tumor suppressor, through selective poly(A) usage, thus contributing to tumor growth in GC." (PMID 34594359, 2021). "However, at least in most ccRCC tumor cases, VHL/pVHL is mutated and loses its function and thus, ccRCC cells become pVHL-deficient." (PMID 34384473, 2021). "In patients with low stage RCC (stages T1–T2), most somatic mutations captured in the tumor tissue were not detectable in either cfDNA or evDNA; however, we did detect a somatic stop-gain mutation of VHL (c.481C > T) in cfDNA sample of patient P2 who was affected by stage T1a tumor." (PMID 34830979, 2021). "More importantly, our work provides another important novel aspect on the potential of this mutation on RCC plasticity, as we noticed that the R167Q VHL mutation regulates the expression of several genes belonging to distinct pathways involved in tumor plasticity, including stemness." (PMID 34359798, 2021). "As the loss of heterogeneity of 3p is a common phenomenon in RCC, especially clear cell RCC, we speculated that loss of ENTPD3-AS1 might promote tumor development in combination with VHL and other tumor suppressor genes." (PMID 34218253, 2021). "There is a complex association between mutations in VHL disease and the tumour phenotypes, with type 2 VHL mutations that result in PCCs having only modest (or minimal) effects on HIF dysregulation, while type 1 mutations do not develop PCCs and result in greater HIF stabilisation." (PMID 34658364, 2021).
tumor (continued). "In recently years, studies have found that lncRNA is involved in the regulation of tumor metabolism, such as lincRNA-p21 is an important player in the regulation of the Warburg effect in cancer cells through attenuating VHL-mediated HIF-1a ubiquitination and causing HIF-1a accumulation." (PMID 34513821, 2021). "Although the optimal surgical timing for resection of VHL-associated CNS HGBs and the effect of radiotherapy and chemotherapy remain unclear, tumor resection is currently the mainstay of therapy for VHL-associated CNS HGBs." (PMID 34109129, 2021). "As HIF2A is stabilised in renal cancer by tumour-initiating mutations in the VHL tumour suppressor, these data provide detailed insight into the mechanisms of interaction between cancer driver mutations and epigenetic events, and how this leads to cancer progression." (PMID 33144692, 2021). "VHL disease is caused by germline mutations of the VHL gene, a tumor suppressor gene." (PMID 33809516, 2021). "The greatest tumor diameter associated with VHL genotype was recently reported." (PMID 34923986, 2021). "Together, these observations support the hypothesis that a discrete VHL point mutation interferes with tumor plasticity and may impact cell behavior by exacerbating phenotypic switching." (PMID 34359798, 2021). "Interestingly, we have seen VHL mutations in only one of the two tumour samples in nine out of eighty-nine patients." (PMID 33946379, 2021). "Gene panel analysis confirmed the VHL gene mutation in the tumor." (PMID 31673890, 2020). "The Von Hippel-Lindau (VHL) gene located on 3p25.5 encodes an ancient tumor suppressor, pVHL." (PMID 33329393, 2020). "Using a case-case analysis, we observed that the 8q24 germline variant rs35252396 was significantly associated with tumor VHL mutation status as well as with the Mayo SSIGN score." (PMID 33121461, 2020). "We hypothesize that the CLN mutation she carries offers a protective effect, preventing tumor development in the cells potentially suffering a VHL second hit mutation." (PMID 32487141, 2020). "Moreover, evidence suggests that VHL-mutated tumours show a stronger activation of HIF target genes compared with tumours with SDH mutations." (PMID 32985654, 2020). "Although HIF promotes the progression of ccRCC, the precise mechanism by which the loss of VHL leads to tumor initiation remains unclear." (PMID 32284789, 2020). "Importantly, SETD2 and BAP1 mutations displayed lower allelic burdens than coexisting VHL mutations, suggesting that these mutations are acquired at later times during tumor development." (PMID 32751108, 2020). "The immunostaining with anti-carbonic anhydrase (CA)-IX was strongly observed in all tumor samples, which would correlate with a pseudo-hypoxic tumor status that is commonly present in this neoplasia and is associated with the VHL mutation, consistent with previous literature reports." (PMID 32620162, 2020). "In our patient, the presence of VHL and Notch2 mutations in both tumors highlights the possibility of using next-generation sequencing to help identify therapeutic targets even in complex composite neoplasms." (PMID 32774962, 2020). "Immunohistochemical analysis confirmed loss of expression of the VHL protein in the tumor cells." (PMID 31673890, 2020). "This high degree of overlap between SDH-loss and VHL-loss signatures is consistent with the hypothesis that both tumor molecular subtypes activate pseudohypoxic signalling." (PMID 31234811, 2019). "In addition, tumor mass was significantly reduced in VHL-deficient RCC than in VHL expressing RCC at end of the experiment." (PMID 30902965, 2019). "It is hence possible that downregulation or loss of CUL5 in ccRCC may further fuel neo-angiogenesis, which plays a central role in ccRCC driven by VHL loss, thus promoting tumor progression." (PMID 30631037, 2019).
tumor (continued). "In the end, our recorded risk group (HR = 3.92, p-value = 2.25 × 10−5), tumor stage (HR = 3.47, p-value = 2.80 × 10−6), age (HR = 1.04, p-value = 3.62 × 10−5), and mutation status of VHL (HR = 0.68, p-value = 0.11) remained as independent prognostic biomarkers." (PMID 31739630, 2019). "Either mutation or deletion of VHL or Itch has profound impact in human diseases such as tumor formation due to VHL mutation or multisystem autoimmune disorders due to Itch deletion, indicating the critical roles of the two E3 ligases in controlling human cell functions." (PMID 30413999, 2019). "In this study, we performed a bioinformatics analysis in a ccRCC dataset showing an association of RSUME levels with VHL mutations and tumor progression, and we demonstrate the molecular mechanism by which RSUME regulates the pathologic angiogenic phenotype of VHL missense mutations." (PMID 30890701, 2019). "In addition, we identified edges in the tumor GCN that are specific to patients with co-occurring VHL and PBRM1 mutations." (PMID 30814637, 2019). "Such inactive form hence accumulated in the VHL-deficient tumor, where it may contribute to the benign nature of the neoplasm." (PMID 30728892, 2019). "Although VHL is the initiating event in ccRCC, the acquisition of additional mutations, some in subclonal cancer cell populations, is a common characteristic during ccRCC tumor development and metastasis." (PMID 31861590, 2019). "Surprisingly, hypoxia-inducible factors were not among the nominated high confidence SDH-loss MRs, although HIF2α (encoded by EPAS1) was nominated as a MR for VHL-loss tumors, controlling ~ 5% of the observed differentially-expressed genes in that tumor subtype." (PMID 31234811, 2019). "The working hypothesis is that, as a classic tumor suppressor gene, VHL will acquire a somatic mutation in the wild-type allele, leading to early tumor development." (PMID 31087189, 2019). "We identified one of the hotspot 5′ UTR mutations in TERT in a VHL patient’s tumor." (PMID 29656891, 2018). "Approximately 40% of the PPGL tumours carry a germ line mutation in one of a number of susceptibility genes of which those that are found in succinate dehydrogenase (SDH) or in von Hippel-Lindau (VHL) genes manifest a strong pseudohypoxic phenotype." (PMID 29450727, 2018). "However, HIF1α expression is lost in 30–40% of overt ccRCCs, since HIF1α acts as a tumor suppressor during further progression of ccRCC by attenuating autonomous VHL-deficient tumor cell proliferation." (PMID 29938199, 2018). "VHL mutations can be used as a genetic proof of the cellular tumor nature." (PMID 29732003, 2018). "In addition, we determined the putative VHL genotype of each tumor sample based on the combination of point mutations and copy number alterations and sorted the samples into homozygous WT (+/+), heterozygous (+/–), and homozygous mutant (–/–) groups." (PMID 29435132, 2018). "VHL mutational status was determined by direct DNA sequencing on tumor tissue." (PMID 30514329, 2018). "Importantly, the ccRCC-derived cell culture retained the VHL driver mutation of the primary human tumor." (PMID 30173145, 2018). "Additionally, 21 CRC-UMF derived from 11 patients were found to display a distinct VHL mutational profile than that found in the corresponding tumor tissue, raising questions regarding their possible tumor or pre-tumor nature." (PMID 30177639, 2018). "Importantly, the changes in DNA methylation in TCGA tumours were similar to those observed in our model system: tumours having mutated VHL had increased DNA methylation compared to those with wild-type VHL." (PMID 30006568, 2018). "Haploinsufficiency of VHL occurs via arm-level loss of chromosome 3p in over 90% of tumours." (PMID 30099580, 2018). "Multifocal ccRCC tumors of distinct origins can be expected in approximately 11.5% of ccRCC cases and could explain the different VHL mutational profiles found in some CRC-UMF with respect to the corresponding tumor sample." (PMID 29732003, 2018).